UBXN10 (UBX domain protein 10)
Description:
VCP/p97-binding protein required for ciliogenesis. Acts as a tethering factor that facilitates recruitment of VCP/p97 to the intraflagellar transport complex B (IFT-B) in cilia. UBX domain-containing proteins act as tethering factors for VCP/p97 and may specify substrate specificity of VCP/p97.
Synonyms: UBXD3; FLJ25429
Tractability: No criterion of Open Targets' tractability assessment is met for any kind of drug.
Gene: Protein-coding gene on chromosome 1 (20,183,293 to 20,196,050, forward strand). Ensembl gene ENSG00000162543.
Subcellular location: Cell projection, cilium
Gene Ontology:
Molecular function: protein binding
Biological process: cilium assembly; ERAD pathway
Cellular component: cilium; intraciliary transport particle B
Genetic constraint (gnomAD): Loss-of-function variants: 7 observed, 9.12 expected, observed/expected ratio (o/e) 0.77, 90% interval 0.44 to 1.43. That is too few expected variants to judge how well the gene tolerates losing a copy. Missense variants: 317 observed, 366.04 expected, observed/expected ratio (o/e) 0.87, 90% interval 0.79 to 0.95. Synonymous variants: 131 observed, 141.81 expected, observed/expected ratio (o/e) 0.92, 90% interval 0.8 to 1.07.
Homologues: Orthologues: chimpanzee UBXN10 (98% identical), macaque UBXN10 (94% identical), pig UBXN10 (75% identical), guinea pig UBXN10 (74% identical), dog UBXN10 (70% identical), mouse Ubxn10 (69% identical), rat Ubxn10 (67% identical), tropical clawed frog ubxn10 (38% identical), zebrafish ubxn10 (26% identical). Paralogues in human: FAF1 (19% identical), FAF2 (17% identical), UBXN7 (16% identical), UBXN8 (13% identical).
Diseases named in the same sentence as UBXN10 in open-access papers:
UBXN10 is named in the same sentence as 10 diseases in open-access papers, as found by Europe PMC text mining. Sharing a sentence is not in itself a finding about the gene and the disease. The quoted sentences say what the papers report.
pulmonary stenosis (1 paper, 2020). "We also report novel plausible gene–disease associations for tetralogy of Fallot/pulmonary stenosis (CDC42BPA, FGD5), hypoplastic left or right heart (SMARCC1, TLN2, TRPM4, VASP), congenitally corrected transposition of the great arteries (UBXN10), and early-onset cardiomyopathy (TPCN1)." (PMID 32037394, 2020).
cancer (2 papers, 2022 to 2024). A tumor composed of atypical neoplastic, often pleomorphic cells that invade other tissues. "For example, most cancer tissues exhibit weak to moderate cytoplasmic and/or nuclear immunoreactivity in the ASPSCR1, UBXN2A, UBXN10, UBXN1, FAF1, FAF2, UBXD2B proteins." (PMID 38365777, 2024).
tumor (2 papers, 2025). "Bulk RNA-seq data from PCa were analyzed to detect the mRNA levels of the model genes, revealing that, except for LTF and UBXN10, the other genes were highly expressed in tumor tissues." (PMID 40161494, 2025).
UBXN10 also shares sentences with these, for which no sentence is quoted: astrocytoma (1 paper); dilated cardiomyopathy (1); Ebstein anomaly (1); gastric cancer (1); glioblastoma (1); heart failure (1); Tetralogy of Fallot (1).